BTBD1 (BTB domain containing 1)
Description:
Probable substrate-specific adapter of an E3 ubiquitin-protein ligase complex which mediates the ubiquitination and subsequent proteasomal degradation of target proteins. Seems to regulate expression levels and/or subnuclear distribution of TOP1, via an unknown mechanism (By similarity). May play a role in mesenchymal differentiation where it promotes myogenic differentiation and suppresses adipogenesis (By similarity).
Synonyms: C15orf1; NS5ATP8
Tractability: PROTAC: ubiquitination databases record sites on it.
Gene: Protein-coding gene on chromosome 15 (83,016,423 to 83,067,281, reverse strand). Ensembl gene ENSG00000064726.
Subcellular location: Cytoplasm
Subcellular location (Human Protein Atlas): Cytoplasmic bodies; Cytosol; Nucleoplasm
Pathways (Reactome):
Immune System: Antigen processing: Ubiquitination & Proteasome degradation
Metabolism of proteins: Neddylation
Gene Ontology:
Molecular function: cullin family protein binding; identical protein binding; protein binding
Biological process: neurogenesis; protein ubiquitination
Cellular component: cytoplasm; cytoplasmic ribonucleoprotein granule; cytosol; protein-containing complex; P-body
Genetic constraint (gnomAD): Loss-of-function variants: 27 observed, 33.7 expected, observed/expected ratio (o/e) 0.8, 90% interval 0.59 to 1.11. The upper end of that interval is the gene's LOEUF score, 1.11, which puts it in group 4 of 6, group 1 being the genes least tolerant of losing a copy. Missense variants: 457 observed, 469.47 expected, observed/expected ratio (o/e) 0.97, 90% interval 0.9 to 1.05. Synonymous variants: 215 observed, 185.37 expected, observed/expected ratio (o/e) 1.16, 90% interval 1.04 to 1.3.
Homologues: Orthologues: chimpanzee BTBD1 (100% identical), macaque BTBD1 (99% identical), dog BTBD1 (99% identical), pig BTBD1 (98% identical), mouse Btbd1 (98% identical), rat Btbd1 (98% identical), guinea pig BTBD1 (95% identical), rabbit BTBD1 (82% identical), tropical clawed frog btbd1 (80% identical). Paralogues in human: BTBD2 (77% identical), BTBD6 (43% identical), BTBD3 (41% identical), BTBD9 (21% identical), ABTB3 (20% identical), ABTB2 (20% identical), KBTBD4 (18% identical), ABTB1 (15% identical), SPOP (15% identical), SPOPL (15% identical), KLHL11 (10% identical).
Diseases named in the same sentence as BTBD1 in open-access papers:
BTBD1 is named in the same sentence as 3 diseases in open-access papers, as found by Europe PMC text mining. Sharing a sentence is not in itself a finding about the gene and the disease. The quoted sentences say what the papers report.
HIV-1 infection (1 paper, 2010). The type species of lentivirus and the etiologic agent of acquired immunodeficiency syndrome (AIDS). "We next evaluated the effect of the BTBD1 and BTBD2 shRNA plasmids transfected individually on permissiveness to HIV-1 infection in COS-1 cells." (PMID 21092135, 2010).
infection (1 paper, 2010). The state of being infected such as from the introduction of a foreign agent such as serum, vaccine, antigenic substance or organism. "In contrast, transfection of BTBD1 shRNA did not increase permissiveness to infection (data not shown)." (PMID 21092135, 2010).
BTBD1 also shares sentences with these, for which no sentence is quoted: tumor (1 paper).